TMEM213 (transmembrane protein 213)
Tractability: Antibody: UniProt predicts a signal peptide or a membrane-spanning region.
Gene: Protein-coding gene on chromosome 7 (138,797,952 to 138,838,101, forward strand). Ensembl gene ENSG00000214128.
Subcellular location: Endoplasmic reticulum membrane
Gene Ontology:
Cellular component: endoplasmic reticulum membrane
Genetic constraint (gnomAD): Loss-of-function variants: 7 observed, 8.97 expected, observed/expected ratio (o/e) 0.78, 90% interval 0.44 to 1.45. That is too few expected variants to judge how well the gene tolerates losing a copy. Missense variants: 119 observed, 122.17 expected, observed/expected ratio (o/e) 0.97, 90% interval 0.84 to 1.13. Synonymous variants: 59 observed, 53.63 expected, observed/expected ratio (o/e) 1.1, 90% interval 0.89 to 1.37.
Homologues: Orthologues: chimpanzee TMEM213 (99% identical), macaque TMEM213 (93% identical), dog TMEM213 (78% identical), pig TMEM213 (78% identical), rabbit TMEM213 (75% identical), guinea pig TMEM213 (73% identical), mouse Tmem213 (68% identical), rat Tmem213 (62% identical).
Diseases named in the same sentence as TMEM213 in open-access papers:
TMEM213 is named in the same sentence as 7 diseases in open-access papers, as found by Europe PMC text mining. Sharing a sentence is not in itself a finding about the gene and the disease. The quoted sentences say what the papers report.
clear cell renal cell carcinoma (2 papers, 2021 to 2022). "TMEM213 has been shown to be downregulated in clear cell renal cell carcinoma with a predicted association with invasion and metastasis, whereas it is upregulated in lung adenocarcinoma and contributes to a longer survival of patients." (PMID 35892586, 2022). "Previously the associations between TMEM213 and TMEM30B and between TMEM72 and TMEM116 have been described, however, for clear cell renal cell carcinoma." (PMID 34638224, 2021).
breast tumors (1 paper, 2022). "The levels of TMEM213 were found to be upregulated upon silencing AKT1 (this study), and an inverse correlation exists between the levels of AKT1 and TMEM213 in breast tumors." (PMID 35892586, 2022).
renal carcinoma (1 paper, 2024). A carcinoma arising from the epithelium of the renal parenchyma or the renal pelvis. "Some proteins of this family are potentially useful for classifying cancer grade in renal cancers (e.g., TMEM45A, TMEM116, TMEM207, TMEM213)." (PMID 38974022, 2024).
tumor (4 papers, 2014 to 2026). "Oppositely to TMEM156, TMEM173, and TMEM213, patients with higher ANO1 expression have a lower fraction of lymphocytes in the tumor microenvironment." (PMID 34638224, 2021). "Transmembrane protein 213 (TMEM213) and Claudin 8 (CLDN8) were detected only in three (0.94 %) and four (1.25 %) tumor specimens, with average folds of 1,066 and 226, respectively." (PMID 24318988, 2014). "TMEM213 showed to be not involved in the modeling of tumor microenvironment." (PMID 34638224, 2021). "That may suggest the important role of TMEM213 in the immune response against the tumor; however, these results are not as conclusive as in the case of TMEM156 and TMEM173." (PMID 34638224, 2021).
cancer (3 papers, 2021 to 2024). A tumor composed of atypical neoplastic, often pleomorphic cells that invade other tissues. "Despite the fact that TMEM213 expression is altered in several cancer types, its role in cancer development and progression, to our knowledge, still remains unknown." (PMID 34638224, 2021).
TMEM213 also shares sentences with these, for which no sentence is quoted: lung adenocarcinoma (2 papers); kidney cancer (1).